TRPM7 (transient receptor potential cation channel subfamily M member 7)
Diseases named in the same sentence as TRPM7 in open-access papers (continued):
Sharing a sentence is not in itself a finding about the gene and the disease.
breast carcinoma (continued). "TRPM7 was reported to regulate breast cancer cell migration through its kinase domain." (PMID 33435261, 2021). "In addition to GC, TRPM7 overexpression also has been shown in pancreatic adenocarcinoma, bladder cancer, and breast cancer cells." (PMID 34938330, 2021). "In addition, although TRPM7 was reported to mediate breast cancer cell migration and invasion, we found that knockout of TRPM7 did not significantly suppress the migration of MDA-MB-231 after 24 h." (PMID 33435261, 2021). "This review focuses on the TRPM7 channel, and the oncogenic roles studied so far in breast cancer." (PMID 34944940, 2021). "The aim of our study is to test the hypothesis that lidocaine affects the viability and migration of breast cancer cells by regulating TRPM7." (PMID 33435261, 2021). "Furthermore, an increased expression of TRPM7 channel is correlated with breast cancer progression and metastasis." (PMID 33617107, 2021). "Furthermore, high expression levels of TRPM7 predict a poor outcome in breast cancers due to increased metastasis as confirmed using mouse xenograft model of human breast cancer." (PMID 34069353, 2021). "Hence, we suggested that lidocaine affects the viability and migration of breast cancer cells by regulating TRPM7." (PMID 33435261, 2021). "Breast cancer patients with an overexpression of TRPM7 have a poor prognosis." (PMID 34944940, 2021). "In breast carcinoma, a pro-survival role of TRPM7 channels has been demonstrated." (PMID 34944940, 2021). "In addition, the inhibition and downregulation of TRPM7 by specific chemical agents is known to inhibit the migration and invasion of breast cancer cells, while overexpression has been shown to support the proliferation and migration of lung cancer cells." (PMID 34938330, 2021). "This suggests the potential of developing modulators of TRPM7 into anti-breast cancer therapeutics." (PMID 34944940, 2021). "Based on these findings, we speculate that overexpression of TRPM7 in breast cancer cells raises their intracellular zinc concentration, which, in turn, increases cellular levels of MDMX to promote cancer cell migration." (PMID 34627839, 2021). "Thus, the TRPM7 channel is involved in the migration and invasion of breast cancer cells via the interaction between its kinase domain and the actomyosin cytoskeleton as well as its contribution to the phosphorylation of Src and MAPKs signaling pathway." (PMID 34944940, 2021). "Here we show that TRPM inhibitors suppressed the viability of TRPM7-expressing breast cancer cells." (PMID 31947967, 2020). "In addition to being an attractive therapeutic target, TRPM7 is also a good prognostic marker for breast cancer." (PMID 32825277, 2020). "To determine whether knock-out of TRPM7 affects breast cancer cell proliferation, we cultured and counted the WT-231 and KO-231 cells." (PMID 31947967, 2020). "Therefore, we chose 2-APB (200 μM, 24 h) in subsequent experiments and used a second inhibitor, Gin Rd, to confirm the effect of TRPM7 inhibition in breast cancer cells." (PMID 31947967, 2020). "In addition, the presence and distribution of TRPM7 in normal human breast tissue was also confirmed at the mRNA and protein levels by studies carried out on human breast cancer." (PMID 32168794, 2020). "Indeed, Kaplan–Meier analysis in breast cancer patients found that the high expression of TRPM7 is significantly correlated with recurrence-free survival and distant metastasis-free survival in breast cancers." (PMID 32211326, 2020). "In summary, TRPM7 is expressed and plays a role in many breast cancers." (PMID 31947967, 2020). "We utilized an online-based RNA expression analyzing web server, GEPIA, to analyze whether the level of expression of the TRPM7 gene in breast cancer affects the overall survival of patients." (PMID 31947967, 2020).
breast carcinoma (continued). "Furthermore, downregulation of TRPM7 is known to inhibit the migration and invasion of breast cancer cells, while up-regulation has been shown to promote migration of lung cancer cells and vascular smooth muscle cells." (PMID 32907556, 2020). "TRPM7 was recently considered as a potential target for breast cancer treatment." (PMID 31947967, 2020). "In breast cancer, TRPM7 was reported to regulate the proliferation of tumor cells." (PMID 32643506, 2020). "TRPM7 is overexpressed and required for proliferation in bladder cancer and breast cancer cells." (PMID 31947967, 2020). "TRPM7 expression predicts metastasis and recurrence in breast cancer and several other cancers." (PMID 30615643, 2019). "Furthermore, TRPM7 expression has been found to be correlated to metastasis as well as invasive breast cancer via activation of the MAPK pathway and is required for MCF7 cell proliferation." (PMID 30223530, 2018). "There are numerous studies showing a clear correlation between cancer patient survival and TRP channel expression, e.g., TRPC1, TRPM2 and TRPV4 in breast cancer, TRPM7 in PDAC, TRPM8 in bladder cancer and osteosarcoma and TRPV2 in breast and esophageal cancer to name just a few examples." (PMID 29772843, 2018). "Silencing of TRPM7 in MDA-MB-435 breast cancer cells leads to a reduced migration." (PMID 29772843, 2018). "Besides pancreatic cancer, TRPM7 is aberrantly over-expressed in the cell lines and tissues of breast cancer and glioblastoma." (PMID 28379203, 2017). "In breast cancer cells, TRPM7 in involved in ginsenoside Rd-induced apoptosis." (PMID 28379203, 2017). "The TRPM7 kinase domain has been reported to phosphorylate CREB peptide in breast cancer cells." (PMID 29273814, 2017). "It is found that TRPM7 is highly expressed in a number of human cancer tissues and cell lines to regulate cell proliferation, migration, and invasion, such as glioblastoma, ovarian cancer, and breast cancer." (PMID 27803760, 2016). "We previously showed that TRPM7 is required for breast cancer cell migration." (PMID 25797249, 2015). "We therefore hypothesized that TRPM7 gene variation may contribute to the pathogenesis of human breast cancer." (PMID 24952306, 2014). "To date, no study has assessed genetic variation in TRPM7 gene or its contribution to susceptibility to breast cancers." (PMID 24952306, 2014). "Thus, these previous reports suggest a functional involvement of the TRPM7 gene in the pathophysiology of breast cancer." (PMID 24952306, 2014). "Patient profile according to TRPM7 expression in basal subtype breast cancer patients." (PMID 25330448, 2014). "TRPM7 was also found to be involved in breast cancer cell metastasis." (PMID 24952306, 2014). "TRPM7 is frequently expressed in the poorly differentiated and highly proliferative breast cancers (grade III, high Ki67), so it may be considered as a proliferative marker of poorly differentiated tumors." (PMID 24952306, 2014). "Moreover, TRPM7 expression was functionally required for the invasive migration and the metastasis formation in a mouse xenograft model of human breast cancer." (PMID 23594099, 2013). "Thus, polymeric nanoparticles could be employed to regulate calcium and magnesium ions in the TRPM7 channel and the supply of ATP to combat the growth, invasion, and metastasis of breast cancer cells." (PMID 41471263, 2025). "Moreover, we found that co-administration of pharmacological inhibitors of HER2 and TRPM7 elicited a synergistic antiproliferative effect on HER2-overexpressing SKBR3 cells but not on HER2-deficient MDA-MB-231 breast cancer cells." (PMID 39513908, 2024). "Therefore, a better understanding of expression and oncogenic function of the TRPM7 channel could give rise to a new generation of therapeutic approaches against breast cancer." (PMID 34944940, 2021). "In addition, although TRPM7 regulates both viability and migration of some breast cancer cells, it might act through different pathways." (PMID 33435261, 2021).
breast carcinoma (continued). "Therefore, TG100-115 could be used as an inhibitor of the kinase activity of TRPM7 and an inhibitor of the migration of breast cancer cells." (PMID 34944940, 2021). "TRPM7 also modulates pathophysiological mechanisms in the mammary gland, either indirectly or directly, including regulation of myosin II-based cellular tension or mitogen-activated protein kinases, as well as being involved in the migration and invasion of breast cancer cells." (PMID 32168794, 2020). "However, a role for this bifunctional channel in cancer progression has been proposed only recently: TRPM7 is critical for cell migration of different cell cancer models such as breast cancer, lung cancer, nasopharingeal cancer and pancreatic ductal adrenocarcinoma." (PMID 24204345, 2013). "In follow-up experiments with HAP1 cells and different cancer cells, we found that TRPM7 regulates the expression of HER2 and that this regulatory mechanism can be exploited for combinatorial pharmacological treatment of HER2-expressing breast cancer cells." (PMID 39513908, 2024). "TRPM7 and TRPM8 has proved act as oncogenes in breast cancer tissues compared with normal tissues, and is correlated with the Scarff-Bloom-Richardson (SBR) grade, Ki67 and tumor size." (PMID 36064388, 2022). "EGF-induced EMT in breast cancer cells results in the transcriptional up-regulation of the efflux transporter ABCC3 in a calcium-dependent manner, but independently of TRPM7 as well as of ORAI1 and STIM1 (component of the store-operated calcium entry pathway)." (PMID 34988012, 2021). "In breast cancer cells MDA-MB-231, AU565 and T47D, a knockout TRPM7, reduced cell growth and the use of 2-aminoethoxydiphenyl borate (2-APB), an inhibitor of TRP channel activity, demonstrates a cell cycle alteration." (PMID 34944940, 2021). "We also discovered that a complex between the proteins can be detected in multiple cell types, including the endogenous TRPM7 and CNNM4 proteins in ZR-75-1 breast cancer cells." (PMID 34928937, 2021). "In breast cancer cell line MCF-7, G-Rd inhibits the activity of the TRPM7 channel, inducing a decrease in cell proliferation and survival as well as activation of apoptosis by apoptotic mechanisms of the intrinsic pathway." (PMID 34944940, 2021). "In breast cancer cell MDA-MB-231, the addition of TG100-115 inhibits the channel activity of TRPM7 and strongly decreases cell migration and invasion, resulting from an inhibition of phosphorylation of the heavy chain of myosin IIA, in this last case." (PMID 34944940, 2021). "In other breast cancer cells, MDA-MB-231, TRPM7 contributes to maintaining a mesenchymal-like phenotype by tensional regulation of the SRY-Box Transcription Factor 4 (SOX4), a recently identified regulator of EMT in breast cancer cells." (PMID 34944940, 2021). "The cell viability of breast cancer cell lines BT-483, BT-474, MCF-7, MDA-MB-231 and MDA-MB-453 was tested and TRPM7 was evaluated in MDA-MB-231, MCF-7 and HEK293 cells." (PMID 33946245, 2021). "In breast cancer cell lines MDA-MB-231 and MCF-7, the addition of carvacrol inhibits TRPM7 currents, increases cell arrest in G0/G1 phase, and decreases cells in the S and G2/M phase, with different sensitivity." (PMID 34944940, 2021). "In human breast cancer cells, MDA-MB-231, the silencing of TRPM7 with shRNA, alters the cell architecture and decreases the metastatic potential." (PMID 34944940, 2021). "In the breast cancer cell line MCF-7, like G-Rd, SR blocks the activity of the TRPM7 channel and activates apoptosis by the apoptotic mechanisms of the intrinsic pathway, inhibiting cell growth and cell survival." (PMID 34944940, 2021). "Another study showed that siRNA‐mediated knockdown of TRPM7 expression in MCF‐7 cells impairs biological functions, highlighting the importance of TRPM7 expression in human breast cancer epithelial cells." (PMID 33617107, 2021). "However, the function of TRPM7 in the viability of breast cancer cells remains unclear." (PMID 31947967, 2020).
breast carcinoma (continued). "Importantly, TRPM7 mediated calcium signals further modulate EMT in breast cancer cells, which TRPM7 deficiency specifically reduces EGF-induced STAT3 phosphorylation and the expression of Vimentin, suggesting that TRPM7 is required for maintaining a mesenchymal feature in breast cancer cells." (PMID 32211326, 2020). "Previously, TRPM7 was found to participate in EMT induced by tension or EGF in breast cancer, and TGF-β in prostate cancer." (PMID 33381038, 2020). "We selected three breast cancer cell lines MDA-MB-231, AU565, and T47D and measured the expression of TRPM7 and the effect of 2-APB on TRPM7 expression in these cells." (PMID 31947967, 2020). "TRPMs have also been recognized as important modulators in multiple cancers progression, from which TRPM2, TRPM7, and TRPM8 have been shown to promote breast cancer development." (PMID 32211326, 2020). "Intracellular calcium regulated by TRPM7 also induces epithelial–mesenchymal transition (EMT), converting epithelial cells to mesenchymal-like cells, crucial for the metastasis of breast cancer." (PMID 32168794, 2020). "TRPM7 silencing reduced the phosphorylation level of MAPK signal molecules (P38, ERK, and JNK) in metastatic breast cancer cells and decreased their migration and invasion." (PMID 32733880, 2020). "Silencing TRPM7 induces a significant reduction in the migration and invasion potential of MDA-MB-435 breast cancer cells, in addition to a decrease in the levels of phosphorylated Src and MAPK." (PMID 29875336, 2018). "The role of different TRPM members has been shown in various cancers such as prostate cancer for mostly TRPM8 and TRPM2, breast cancer for mostly TRPM2 and TRPM7, and pancreatic cancer for TRPM2/7/8 channels." (PMID 29875336, 2018). "TRPM7-mediated migration and invasion of MDA-MB-435 breast cancer cells especially involved the mitogen-activated protein kinase (MAPK) signaling pathways." (PMID 29875336, 2018). "It was recently reported that the TRPM7 kinase domain is able to directly phosphorylate CREB peptide and full-length CREB in breast cancer cells." (PMID 29273814, 2017). "Down-regulation of TRPM7 decreases the level of p-Akt in OVCA cells and human lung fibroblasts, and also decreases the level of p-ERK1/2 in breast cancer cells." (PMID 25965832, 2015). "Interestingly in lung cancer cells A549, EGF functionally regulates TRPM7 expression at the plasma membrane thus increasing cell migration rate while TRPM7 protein downregulation significantly interferes with the metastatic potential of human breast cancer in vivo." (PMID 24204345, 2013). "TRPC1, TRPM7 and TRPM8 expression strongly correlated with proliferative parameters, and TRPV6 was mainly overexpressed in invasive breast cancer cells." (PMID 22692672, 2012). "TRPM7 is overexpressed in poorly differentiated and highly proliferative breast cancer, while TRPM8 is mainly overexpressed in highly differentiated and poorly proliferative breast cancer." (PMID 39633507, 2024). "Given the exceptional importance of HER2 for treating breast cancer, we performed proof-of-principle experiments to show that combined pharmacological inhibition of HER2 and TRPM7 elicits synergistic antiproliferative effects on HER2-positive breast cancer cells." (PMID 39513908, 2024). "TRPM7 may promote tumor metastasis by contributing to the EMT process, and this ability has been demonstrated in mouse xenotransplantation models of breast cancer." (PMID 39633507, 2024). "In this study, we found that TRPM7 was highly expressed in the luminal A subtype of breast cancers but no other subtypes compared with GTEx (Genotype-Tissue Expression Rad) or normal samples by analyzing the TCGA database." (PMID 36064388, 2022). "In this respect, the TRPM7 channel reduces the cytoskeletal stress by inhibiting myosin II activity, which mechanistically activates SOX4 expression and, therefore, contributes to metastatic processes of breast cancer cells." (PMID 36844925, 2022).
breast carcinoma (continued). "Overexpression of TRPM7 has a poorer survival result in breast cancer and has a negative effect on the progressive tumor behavior of gastric cancer and the prognosis of patients." (PMID 36363540, 2022). "The TRPM7 inhibitor 2-aminoethyl diphenylborinate (2-APB) attenuates MDA-MB-231, AU565, and T47D cell proliferation, increasing S phase and decreasing G0/G1 phase in the breast cancer cell cycle." (PMID 33806911, 2021). "Increased Ca2+ through TRPC1, TRPM7/8, P2X7, and SOCC enhances breast cancer cell migration." (PMID 33806911, 2021). "Importantly, we found that TRPM7 inhibition, like TPEN treatment, decreases breast cancer cell MCF-7 proliferation and migration." (PMID 34627839, 2021). "In human breast cancer cells, MDA-MB-231, the use of 2-APB or silencing of TRPM7 with siRNA significantly decreases intracellular calcium, resulting in total inhibition of mineralization, strongly suggesting a functional role for the channel in the development of hydroxyapatite crystals." (PMID 34944940, 2021). "RT-QPCR results showed that TRPM7 mRNA was expressed in these breast cancer cell lines and that the expression was not significantly changed by a 24-h treatment with 2-APB." (PMID 31947967, 2020). "Gin Rd, which is also not specific to TRPM7, was shown to induce apoptosis in TRPM7-expressing gastric and breast cancer cells." (PMID 31947967, 2020). "In the present study, the expression of TRPM7 in breast cancer cell lines was not affected by 2-APB." (PMID 31947967, 2020). "A decreased expression of TRPM7 was reported to induce apoptosis in bladder cancer cells, but here we found that apoptosis was low in breast cancer cells and independent of the presence of TRPM7." (PMID 31947967, 2020). "Except TRPM7, TRPM8 has also been reported to modulate EMT in breast cancer cells." (PMID 32211326, 2020). "Additionally, TRPM7 siRNA reduced activation of Src, p38 MAPK, ERK1/2 and JNK in a breast cancer cell line." (PMID 30995736, 2019). "TRPM7 and TRPM8 expression was shown to be correlated with breast cancer." (PMID 29875336, 2018). "Additionally, silencing TRPM7 in OVCA cells or human lung fibroblast decreased the level of p-Akt, and in breast cancer cells, p-ERK1/2 was reduced." (PMID 28061441, 2017). "TRPM7 downexpression decreases the phosphorylation of p-Akt in ovarian cancer cells and lung fibroblasts and also decreases the phosphorylation of p-ERK1/2 in breast cancer cells." (PMID 27803760, 2016). "Indeed, we showed that TRPM7, a TRP-cation channel with kinase activity, directly interacts with the actomyosin cytoskeleton and controls cell-matrix interactions in breast cancer cells as well as in neuroblastoma cells." (PMID 25797249, 2015). "Moreover, the TRPM7 channels exert a cytoskeletal stress-reducing effect by inhibiting the activity of myosin II, which mechanistically triggers the activation of SOX4 expression and thus contributes to the metastatic process in breast cancer cells." (PMID 40078961, 2025). "However, the limitation of our study is that we do not determine the reason why methylation frequency of TRPM7 varies in different subtypes of breast cancer, and the relationship between TRPM7 methylation and gene expression status." (PMID 36064388, 2022). "In addition, TRPM7 induces breast cancer migration regardless of the cellular subtypes (MDA-MB-231 and MCF-7)." (PMID 33806911, 2021). "TRPM7 is not unique among proteins that are relevant to zinc biology in regard to breast cancer." (PMID 34627839, 2021). "Indeed, in breast cancer cell lines MDA-MD-231 and MDA-MD-468 (TNBC cells), NS8593 suppresses TRPM7 Mg2+-dependent currents, increasing the apoptotic and antiproliferative effects induced by TRAIL via a decrease in c-FLIP as well as suppressing the phosphorylation of STAT3, respectively." (PMID 34944940, 2021).